RAB11A (RAB11A, member RAS oncogene family)
Diseases named in the same sentence as RAB11A in open-access papers (continued):
Sharing a sentence is not in itself a finding about the gene and the disease.
infection (continued). "In infection, ATG9A mediates the removal of Rab11a-recycling endosomes carrying vRNPs from microtubules." (PMID 37983294, 2023). "First, given that the cytoplasmic content of vRNPs increases as infection progresses and that vRNPs bind Rab11a (via PB2 viral protein), we have shown that vRNPs outcompete Rab11a adaptors/molecular motors for Rab11a binding." (PMID 37983294, 2023). "In this case, we explored the link between Rab11a and ATG9A at 10 h after infection, as the GFP-Rab11 DNlow cells produce low levels of viral particles before this period (by plaque assay)." (PMID 37983294, 2023). "These membrane-enclosed small vesicles are involved in the infection process by modulating the host cellular responses, and RNA viruses like RSV attach to Rab11a-positive exosomes to reach the plasma membrane for egress from host cells." (PMID 35263387, 2022). "In summary, our data show a novel role for Rab11a in the IAV life cycle, where it can mediate vesicular transport of vRNPs across TNTs and seed new infections." (PMID 34473799, 2021). "On the other hand, infection with multisegmented RNA viruses such as IAV and IBV resulted in increased stalling of Rab11A motion, indicated by an increase in arrest coefficients and a decrease in mean speed." (PMID 31911620, 2020). "For instance, EspF recruits clathrin, AP2, early (Rab5a and EEA1) and recycling (Rab4a, Rab11a, Rab11b, FIP2, Myo5b) endocytic proteins to sites of infection." (PMID 31947656, 2020). "Here, we analyze co-transport between Rab11A and IAV vRNP during a productive infection, in a relevant cell line, and with three-dimensional resolution." (PMID 31911620, 2020). "A representative image of EPEC-wt infected cells (t = 15; yellow arrow) and quantitative analysis of the time-dependent accumulation of photoconverted Rab11a at EPEC-wt and EPEC-escV infection sites are shown." (PMID 31242273, 2019). "We therefore investigated the T3SS dependence of the distribution of clathrin endocytic (CHC, AP2-α, Rab5a and EEA1) and recycling [Rab11a, Rab11b, Rab25, Myosin 5b (Myo5b)] components upon EPEC infection of polarized MDCK cells." (PMID 31242273, 2019). "We show that type-III secreted components prompt the recruitment of clathrin (clathrin and AP2), early (Rab5a and EEA1) and recycling (Rab4a, Rab11a, Rab11b, FIP2, Myo5b) endocytic machineries to peripheral plasma membrane infection sites." (PMID 31242273, 2019). "Further, a number of these CIE regulators, including Rab11a, Hook1, ACAP1/2, and EHD3, are targeted by microRNAs or downregulated by infection with HCMV." (PMID 30042195, 2018). "Prior to infection, A549 cells were treated with RAB11A-specific siRNAs or Non-Target (NT) siRNAs, and RAB11A knock-down efficiency was confirmed by western blot analysis and by immunofluorescence." (PMID 40668844, 2025). "Our proposed model is that during infection, progeny vRNPs attach outwardly to Rab11a recycling endosomes and are trafficked together, not to the surface as previously thought, but instead toward the ERES." (PMID 37983294, 2023). "We show that complexes of Rab11a and viral components can be trafficked across tunneling nanotubes, transmitting infection without the formation of virus particles." (PMID 34473799, 2021). "To support our hypothesis that segmented viruses manipulate the movement of Rab11A differently than single-stranded RNA viruses like RSV, we examined the movement during infection with influenza B virus (IBV)." (PMID 31911620, 2020). "Subsequent experiments revealed differential viral manipulation of Rab11A-RE cellular transport properties during infection by different negative-stranded RNA viruses." (PMID 31911620, 2020). "Quantitation of Rab11a/Rab35-positive CCVs revealed that while Rab11a interacts with the CCV more at 3 dpi, Rab35 is significantly more prevalent at CCVs at 6 dpi, suggesting that the CCV preferentially interacts with Rab11a and Rab35 depending on the stage of infection." (PMID 38841112, 2024).
infection (continued). "To test whetherthe loss of Rab11a had an impact on TNT formation, we counted the number of TNTs formed between cells in WT and Rab11a KO cells in the presence and absence of NL09 infection." (PMID 34473799, 2021). "Results of high MOI infection experiments, in which we only observed a 10-fold decrease in viral titers, suggest that vRNPs can be incorporated into nascent virions in the absence of Rab11a." (PMID 33970958, 2021). "Infection of these cells with EPEC-wt resulted in significant Tfn and Rab11a recruitment in Myo5b-FL or Myo5b-tail-YEQR, but not in Myo5b-tail or Myo5b-tail-QLYC expressing cells." (PMID 31242273, 2019). "Notably, in contrast to Rab11A-WT parasites, GRA16-positive DGs were also retained within Rab11A-DN parasite cytosol and accordingly GRA16 no longer reached the host cell nuclei 16h post-infection." (PMID 32463830, 2020).
cancer (63 papers, 2010 to 2025). A tumor composed of atypical neoplastic, often pleomorphic cells that invade other tissues. "Distinguishing the different classes of tumour EV that are produced under metabolic stress should assist in determining what cancer‐relevant functions are associated with each specific EV subtype, as we have done for Rab11a‐exosomes." (PMID 32720716, 2020). "The Rab11 family (Rab11a, Rab11b and Rab25) is associated with recycling endosomes, and only Rab25 was previously reported as being associated with cancer." (PMID 29285267, 2017). "Rab11a, an evolutionarily conserved Rab GTPases, plays important roles in intracellular transport and has been implicated in cancer progression." (PMID 28468127, 2017). "Notably, transfection with a plasmid encoding siRNA-resistant GFP-Rab11a resulted in a statistically significant and complete rescue of the cytokinetic defects caused by Rab11a downregulation in cancer cells." (PMID 40877912, 2025). "Dysregulation of Rab11a has been implicated in the progression of several cancers." (PMID 33178272, 2020). "Recently Rab11a dysregulation has been implicated in several cancers." (PMID 33178272, 2020). "Rab11a/b has been demonstrated to facilitate cancer cell invasion by promoting the formation of filopodium-tipped protrusions, suggesting a link between the Rab11 family and F-actin nucleation that extends beyond formation of tracks for vesicles." (PMID 40614209, 2025). "Previous studies found that RAB11A plays a critical role in cancer malignant progression through regulating the growth factor signaling." (PMID 36760469, 2023). "Our Chmp5 knockdown studies in both flies and human cancer cell lines suggest that Rab11a‐exosomes perform specialised physiological and pathological functions." (PMID 36872252, 2023). "Several studies reported that the upregulation of RAB11FIP1 and RAB11FIP2 and their interacting partner RAB11a promotes cancer migration and invasion." (PMID 34983537, 2022). "It has been demonstrated that RAB11A can regulate the proliferation and motility of cancer cells via Wnt signaling pathway." (PMID 36187840, 2022). "miR-944 can also inhibit the EMT process of cancer cells by participating in the SNHG6/miR-944/RAB11A axis." (PMID 36077769, 2022). "In pituitary adenoma (PA), the SNHG6/miR-944/RAB11A axis promotes cancer cell proliferation, invasion, migration, and EMT." (PMID 36077769, 2022). "It was reported that Rab11a contributed to cancer growth and invasion and was a target of miR-320a in breast cancer." (PMID 33178272, 2020). "Glutamine depletion induces a switch in the balance of exosome marker secretion in cancer cells from CD63 to Rab11a, a result observed with two very different EV isolation methods." (PMID 32720716, 2020). "As with Rab25, Rab11a has been reported to have both tumour-promoting and tumour-suppressing roles in cancer." (PMID 32842549, 2020). "Rab11a protein expression was obviously higher in 7 of 10 cancer tissues compared with their corresponding normal tissues." (PMID 33178272, 2020). "Since glutamine is now recognised as a key metabolite in several cancers, glutamine depletion is likely to be a common event in growing tumours, which would trigger a switch to Rab11a‐exosome secretion." (PMID 32720716, 2020). "While there is minimal knowledge about the role of Rab11A in GPCR-driven cancer progression, Rab11A has been shown to recruit Gβγ to endosomes and sustain lysophosphatidic acid (LPA) activated Akt signaling, which is associated with LPA-induced cell survival." (PMID 29954076, 2018). "Both Rab11A and Rab11B show significant changes in expression in various human cancer types with a prevalence for Rab11A." (PMID 29954076, 2018). "Studies have indicated that recycling members (Rab11a, Rab11b, Rab25/Rab11c as well as their effectors) exert an important role in cancers of multiple lineages, including breast, colon, lung, ovarian, renal, endometrial, prostate, bladder and carcinoid types." (PMID 25815277, 2015).
cancer (continued). "In fact, in other contexts, overexpression of Rab11a has been shown to contribute to the proliferation and invasion of cancer cells via increased signaling of ERK, PI3K/AKT, EGFR, WNT, and MMP2, consistent with our findings that increased Rab11 activity can drive angiogenesis." (PMID 38903077, 2024). "We conclude that accessory ESCRT‐III components have a specific, ubiquitin‐independent role in Rab11a‐exosome generation, a mechanism that might be targeted to selectively block pro‐tumorigenic activities of these vesicles in cancer." (PMID 36872252, 2023). "In cancer cells, Rab11a‐exosome secretion is induced by metabolic stresses via suppression of nutrient‐sensitive mechanistic Target of Rapamycin Complex 1 (mTORC1) signalling, while exosome secretion from late endosomes is reduced, at least partly via a switch in endosomal trafficking." (PMID 36872252, 2023). "Next, we determined the influence of RAB11A on the invasion and migration of cancer cells." (PMID 36760469, 2023). "RAB11A, a member of the GTPase family, acts as a regulator in diverse cancers development." (PMID 36760469, 2023). "In cancer cells, Rab11a‐exosomes appear to have novel functions that may be involved in adaptive responses." (PMID 36872252, 2023). "It has been reported that RAB11A is overexpressed in cancers and promotes cancer progression." (PMID 33226737, 2021). "We hypothesized that RAB11A endosomes are required for monitoring tumorigenic signaling and can thus impact colonic tumorigenesis and cancer development." (PMID 34058200, 2021). "A recent publication reported that the depletion of glutamine from the TME causes a shift in the subtype of cancer EVs that are released; switching from late-endosomal CD63-positive exosomes towards RAB11a-positive exosomes that originate from recycling endosomes and promote tumor vascularization." (PMID 33321449, 2021). "Recent evidences suggested Rab11a as a cancer-related protein." (PMID 33178272, 2020). "There is a link between the function of Rab11a in GC and in other cancers." (PMID 33178272, 2020). "Furthermore, preferential release of Rab11a‐marked exosomes from these compartments is triggered by depleting cancer cells of exogenous glutamine." (PMID 32720716, 2020). "Nude mice xenograft demonstrated that Rab11a promoted in vivo cancer growth." (PMID 28468127, 2017). "In addition, the mechanism of Rab11a in cancer proliferation and invasion remains unclear." (PMID 28468127, 2017). "Consistent with previous experiments using HCT116 Rab11a‐exosome preparations and HCT116 target cells and with other cancer sEVs, this effect was blocked by a neutralising anti‐AREG antibody, which suppressed the sEV‐induced activation via phosphorylation of the downstream signalling target ERK." (PMID 38887984, 2024). "Previous studies have shown that RAB10, RAB11A, RAB17, and RAB25 could promote cell proliferation in different cancers." (PMID 35154286, 2022). "We analyzed the grey value of western blot bands and found that average expression of Rab11a in cancer tissues was significantly higher than that in normal tissues (Student's t test, p < 0.05)." (PMID 28468127, 2017). "The expression and function of Rab11a in human cancers have not been well investigated." (PMID 28468127, 2017). "It is possible that selective inhibition of Rab11a‐exosome biogenesis by interfering with accessory ESCRT‐III function in such tumours could block adaptive responses without preventing other important events, such as the ubiquitin‐mediated degradation of growth factor receptors in cancer cells." (PMID 36872252, 2023).
tumor (52 papers, 2011 to 2026). "RAB11A serves as a target molecule involved in various microRNA-mediated tumor suppression processes." (PMID 39479501, 2024). "In this study, we illustrated the tumor-promoting effects of RAB11A based on in vivo and in vitro experiments." (PMID 36760469, 2023). "We have previously proposed that stress‐induced Rab11a‐exosomes are likely to be involved in tumour adaptation mechanisms." (PMID 36872252, 2023). "The exocyst interacts with the small GTPase Rab11A that binds to MVBs, mediates the process of Rab11A transporting MVBs to the plasma membrane, and promotes the secretion of exosomes from tumor cells." (PMID 38203424, 2023). "miR-140-5p, as the downstream target gene of KCNQ1OT1, targets and regulates the downstream RAB11A, and it is involved in the proliferation and tumor progression of PA." (PMID 35432529, 2022). "We found that RAB11A controls the biochemical associations of YAP with multiple components of adherens and tight junctions, including α-catenin, β-catenin, and Merlin, a tumor suppressor." (PMID 34058200, 2021). "The detection of just a partial colocalization with calnexin and Rab11A seems to suggest anyway that HA is mainly localized in the cytoplasm of the MPM tumor cells." (PMID 33499323, 2021). "In our study, we found that RAB11A expression was upregulated and had an opposite expression pattern with miR-30a-5p in PC tumor tissues." (PMID 33292272, 2020). "Lastly, tumorigenicity assay in vivo demonstrated that NORAD increased tumor volume and weight via miR-30a-5p /RAB11A pathway." (PMID 33292272, 2020). "The expression of RAB11A was decreased in the tumor tissues with injection of PC-3 cells transfected with NORAD siRNA, and miR-30a-5p inhibitor weakened this result." (PMID 33292272, 2020). "Then, we measured the expression of RAB11A mRNA in PC tumor tissues and adjacent normal tissues, and the results showed that RAB11A mRNA expression was notably upregulated in PC tumor tissues." (PMID 33292272, 2020). "In pancreatic cancer, Rab11A expression correlates with tumor-node-metastasis stage and promotes cell proliferation, cell cycle progression and invasion through GSK3β/Wnt/β-catenin pathway." (PMID 29954076, 2018). "The volume of xenograft tumor of Rab11a overexpressed stable cells increased compared with that of the control plasmid-transfected cells." (PMID 28468127, 2017). "RAB11A is a RAS oncogene family member expressed in tumor cell lines and suggested to be involved in membrane trafficking." (PMID 22675446, 2012). "We propose that this Rab11a‐exosome‐mediated mechanism contributes to the establishment of resistance in cetuximab‐sensitive cells and may explain why in cetuximab‐resistant tumours only some cells carry mutant KRAS." (PMID 38887984, 2024). "Furthermore, the interference of RAB11A reduced the tumor growth and the protein levels of p-FAK/FAK and p-AKT/AKT in vivo." (PMID 36760469, 2023). "Our data suggests that the decreased expression of Rab11a in tumor cells will alter their composition, which might also result in the secretion of exosomes with lower pro-tumoral effect." (PMID 36986603, 2023). "Previous studies confirmed that changes in RAB11A expression could affect the proliferation and apoptosis of tumor cells significantly." (PMID 35432529, 2022). "Release of Rab11a‐exosomes under metabolic stress provides a mechanism for generating the heterogeneity in tumours that might drive adaptive changes." (PMID 32720716, 2020). "Therefore, glutamine depletion or mTORC1 inhibition stimulates release from Rab11a compartments of exosomes with pro‐tumorigenic functions, which we propose promote stress‐induced tumour adaptation." (PMID 32720716, 2020). "Whether Rab11A plays a key role in modulating the compartmentalized signaling of GPCRs and/or PARs to regulate tumor progression remains to be investigated." (PMID 29954076, 2018). "Rab11a protein was mainly located in the cytoplasmic compartment of tumor cells." (PMID 28468127, 2017).
tumor (continued). "The Rab25 targeting peptide, RFP14, preferentially binds to Rab25 over Rab11a and inhibits cell proliferation and migration in the breast cancer cell lines in which Rab25 is oncogenic, but augments these phenotypes in the cell lines in which it is tumour-suppressive." (PMID 32842549, 2020). "We have shown that this resistance can be mediated by AREG‐loaded, Rab11a‐exosomes produced by CRC cells under nutrient or hypoxic stresses, which are commonly experienced by growing tumours." (PMID 38887984, 2024). "NORAD promoted cell proliferation, invasion and EMT via the miR-30a-5p/RAB11A/WNT/β-catenin pathway, thus inducing PC tumor growth." (PMID 33292272, 2020). "Overexpression of Rab11a is correlated with positive nodal status, advanced Tumor Node Metastasis (TNM) stage and poor patient prognosis." (PMID 38695990, 2024). "Our study found that Rab11a increased invasion ability and positively regulated MMP2, a potent protease that could degrade ECM and promotes tumor cell invasion, suggesting Rab11a promotes invasion through MMP2." (PMID 33178272, 2020). "We confirmed these results via Western blotting analysis of tumor cells expressing AFAP1-AS1 siRNA, and found that RhoA, Rac2, Rab10, Rab11a, Rhogdi and Pfn1 were significantly upregulated, but RhoC, Rab11b and Lasp1 were significantly downregulated in NPC cell lines." (PMID 26246469, 2015). "Among them, RAB11A expression was correlated with the expression of UPK1A and UPK2, two urothelium marker genes also down-regulated in this tumor group (data not shown)." (PMID 22724020, 2012).
neurodegenerative disease (7 papers, 2015 to 2025). A disorder of the central nervous system characterized by gradual and progressive loss of neural tissue and neurologic function. "Future research could focus on exploring the specific functions of RAB11A and assessing the effectiveness of potential treatment approaches in the model, such as the relationship between autophagy, endosome–lysosome transport and neurodevelopmental and neurodegenerative diseases." (PMID 40959816, 2025).
bacterial infection (3 papers, 2014 to 2019). "Ectopically expressed Myo5b-FL co-clustered with Rab11a and basolaterally internalized Tfn at apical bacterial infection sites." (PMID 31242273, 2019). "Next, we aimed at identifying type III secreted effectors that might mediate the clustering of Rab11a and Tfn-positive endosomes at bacterial infection sites." (PMID 31242273, 2019). "The GTPase RAB11A is involved in recruitment of TLR4 to phagosomes and IRF3 signaling, both of which are key events in the innate immune response and host defenses against bacterial infection and are highly relevant for IBD." (PMID 25927528, 2015).